P2RY14 (purinergic receptor P2Y14)
Description:
Receptor for UDP-glucose and other UDP-sugar coupled to G-proteins. Not activated by ATP, ADP, UTP or ATP.
Synonyms: P2Y14; GPR105; KIAA0001; BPR105
Tractability: Small molecule: a high-quality ligand is known; it belongs to a druggable protein family. Antibody: its Gene Ontology location is reachable by antibodies, with high confidence; UniProt places it where antibodies can reach, with medium confidence; UniProt predicts a signal peptide or a membrane-spanning region. PROTAC: a small molecule that binds it is known.
Target class: Purine receptor; Small molecule receptor (family A GPCR); Membrane receptor; Family A G protein-coupled receptor; Nucleotide-like receptor (family A GPCR)
Chemical probes: PPTN (high quality)
Gene: Protein-coding gene on chromosome 3 (151,212,115 to 151,278,811, reverse strand). Ensembl gene ENSG00000174944.
Subcellular location: Cell membrane
Pathways (Reactome):
Signal Transduction: G alpha (i) signalling events; P2Y receptors
Gene Ontology:
Molecular function: G protein-coupled purinergic nucleotide receptor activity; G protein-coupled UDP receptor activity; G protein-coupled receptor activity
Biological process: G protein-coupled receptor signaling pathway; G protein-coupled purinergic nucleotide receptor signaling pathway
Cellular component: membrane; plasma membrane
Genetic constraint (gnomAD): Loss-of-function variants: 7 observed, 6.08 expected, observed/expected ratio (o/e) 1.15, 90% interval 0.64 to 1.85. That is too few expected variants to judge how well the gene tolerates losing a copy. Missense variants: 378 observed, 420.44 expected, observed/expected ratio (o/e) 0.9, 90% interval 0.83 to 0.98. Synonymous variants: 158 observed, 156.06 expected, observed/expected ratio (o/e) 1.01, 90% interval 0.89 to 1.15.
Homologues: Orthologues: chimpanzee P2RY14 (99% identical), macaque P2RY14 (98% identical), dog P2RY14 (84% identical), pig P2RY14 (84% identical), rabbit P2RY14 (84% identical), guinea pig P2RY14 (83% identical), mouse P2ry14 (83% identical), rat P2ry14 (80% identical), tropical clawed frog p2ry14 (52% identical), zebrafish P2RY14 (40% identical). Paralogues in human: GPR87 (44% identical), P2RY12 (44% identical), P2RY13 (41% identical), GPR171 (30% identical), GPR34 (30% identical), PTAFR (23% identical).
Diseases named in the same sentence as P2RY14 in open-access papers:
P2RY14 is named in the same sentence as 47 diseases in open-access papers, as found by Europe PMC text mining. Sharing a sentence is not in itself a finding about the gene and the disease. The quoted sentences say what the papers report.
lung carcinoma (7 papers, 2015 to 2023). "And only purinergic receptors P2RX1, P2RX2, P2RX7, P2RY12, P2RY13, and P2RY14 were associated with good prognosis in the lung cancer." (PMID 32638267, 2020). "Two other genes previously implicated in lung cancer, P2RY14 and PAPPA 41,42, were also expressed at significantly higher levels when HES6 was overexpressed." (PMID 25864518, 2015). "However, P2RX1, P2RX7, P2RY12, P2RY13, and P2RY14 were relatively downregulated in lung cancer tissues and were associated with a favourable prognosis." (PMID 33501930, 2021). "However, purinergic receptors P2RX1, P2RX7, P2RY12, P2RY13, and P2RY14 were relatively downregulated in lung cancer tissues and were associated with favorable prognosis." (PMID 32638267, 2020). "A recent article used TCGA data analysis and found that P2RY14 expression is down-regulated in lung cancer tissues." (PMID 34306014, 2021). "We also showed that contrast with the unfavorable prognosis of pyrimidine metabolic rate–limiting enzymes, purinergic receptors P2RX1, P2RX2, P2RX7, P2RY12, P2RY13, and P2RY14 were favorable prognostic markers in patients with lung cancer." (PMID 32638267, 2020). "created a novel Lung cancer prediction model that integrates 5 PyMGs, including P2RX1, P2RX7, P2RY12, P2RY13, and P2RY14, which might be utilized to predict prognosis in Lung cancerpatients." (PMID 37664033, 2023).
asthma (6 papers, 2021 to 2024). "Although there are studies on expression quantitative trait loci (eQTL) suggesting a P2RY14 association with asthma, to our best knowledge renal phenotypes have not been associated with DNA variants in the human P2RY14 gene." (PMID 37250906, 2023). "Notably, P2RX1, P2RX4, P2RX7, P2RY1, P2RY11, and P2RY14 were revealed as the most highly expressed purinergic receptors in lung tissue, therefore suggesting that these receptors have good potential as therapeutic targets for asthma and other respiratory diseases." (PMID 35386996, 2021). "Lack of functional P2RY14 gene in mice is reported to result in decreased airway eosinophilia and airway hyperresponsiveness relative to wild-type mice in mice models of asthma." (PMID 39723337, 2024).
head and neck cancer (3 papers, 2021 to 2023). A primary or metastatic malignant neoplasm affecting the head and neck. "In head and neck cancer, P2RY14 is also a potential biomarker for immune regulation of the tumor microenvironment and good prognosis." (PMID 36950684, 2023). "P2RY14 has been suggested to be a biomarker of tumor microenvironment immunomodulation and favorable prognosis in patients with head and neck cancer." (PMID 35937997, 2022). "In this study, we further analyzed the possible role of P2RY14 in the immune status of head and neck cancer TME." (PMID 34306014, 2021). "Finally, Gene Set Enrichment Analysis (GSEA) was used to explore the molecular mechanism of P2RY14 in the immune modulation of head and neck cancer." (PMID 34306014, 2021). "P2RY14 has been reported to inhibit UDP-glucose-stimulated chemotaxis of human neutrophils, which prompted further analysis of the relationship between P2RY14 gene expression and neutrophil levels in head and neck cancer." (PMID 34306014, 2021).
ovarian carcinoma (3 papers, 2023 to 2024). A malignant neoplasm originating from the surface ovarian epithelium. "The overexpression of P2RY14, a G protein-coupled receptor, has been associated with improved overall survival and longer progression-free intervals in ovarian cancer patients." (PMID 37835417, 2023). "The findings of our study indicate a potential correlation between low expression of P2RY14 and unfavorable prognostic outcomes in ovarian cancer." (PMID 39440060, 2024). "This leads to the maintenance of low P2RY14 expression, which, in turn, correlates with poor prognosis and increased tumor immune infiltration in ovarian carcinoma." (PMID 37835417, 2023). "Using qRT-PCR, we also found that P2RY14 was expressed at lower levels in ovarian cancer cell lines relative to normal cells." (PMID 36950684, 2023). "Comparing ovarian cancer tissues with healthy ovarian tissues, P2RY14 protein expression levels were much higher in normal tissues." (PMID 36950684, 2023). "Additionally, our findings suggest that downregulation expression of P2RY14 facilitates the proliferation and migration of ovarian cancer cells, potentially contributing to the unfavorable prognosis associated with this disease." (PMID 39440060, 2024). "P2RY14 may act as a tumor suppressor gene in ovarian cancer, and further experiments are needed to ascertain its definitive role." (PMID 39440060, 2024).
acute kidney injury (2 papers, 2023 to 2025). Sudden and sustained deterioration of the kidney function characterized by decreased glomerular filtration rate, increased serum creatinine or oliguria. "Consequently, genetical loss or pharmacological inhibition of P2ry14 turned out to be protective against acute kidney injury in a mouse model of ischemia reperfusion injury." (PMID 37250906, 2023). "In the light of the protective effect of P2ry14 inhibition in a mouse model of acute kidney injury this might be a promising field of future research." (PMID 37250906, 2023).
acute leukemia (2 papers, 2018 to 2020). A clonal (malignant) hematopoietic disorder with an acute onset, affecting the bone marrow and the peripheral blood. "Hereafter, PI3K/AKT pathway inhibition is regarded as a therapeutic approach followed by the preclinical studies in leukemia cells in spite of the upregulated expression of P2RY14 in acute leukemia cells resistant to PI3K/mTOR inhibition." (PMID 32333246, 2020). "Taken together, our data suggest that acute leukemia cells resistant to PI3K/mTOR inhibition display upregulation of a GPCR, P2RY14, which has a role in patient survival and also couples to the activation of ERK signaling." (PMID 29951132, 2018).
head and neck squamous cell carcinoma (2 papers, 2021 to 2023). A squamous cell carcinoma that arises from any of the following anatomic sites: lip and oral cavity, nasal cavity, paranasal sinuses, pharynx, larynx, and salivary glands. "Conversely, down-regulation of P2RY14 in head and neck squamous cell carcinoma (HNSC) patients was associated with poor prognosis and reduced immune infiltration, indicating a conversion from immune-dominant to metabolic-dominant status." (PMID 37584707, 2023).
liver fibrosis (2 papers, 2024). "Among which, TGF-β1 contributes to liver fibrosis through facilitating extracellular matrix deposition via TGF-β1/Smad axis in HSCs, while UDP-glucose/UDP-fructose recognizes purinergic receptor P2Y14 distributed in HSCs, resulting in the activation of HSCs and liver fibrosis." (PMID 39071804, 2024).
neurofibroma (2 papers, 2022). An intraneural or extraneural neoplasm arising from nerve tissues and neural sheaths. "At this age, P2ry14 loss decreased Ki67+ cells in neurofibroma tissue sections; many of these proliferative cells expressed the SC marker CNPase." (PMID 35311647, 2022). "Western blot also showed expression in human SCs and neurofibroma SCPs, with 1.9-fold increase of P2ry14 protein in SCP-like cells." (PMID 35311647, 2022). "We found that human neurofibroma-derived SCP-like cells sorted for GPCR P2ry14 expression have increased self-renewal potential." (PMID 35311647, 2022). "Short-term treatment with the P2ry14 inhibitor also decreased cell proliferation (Ki67+ cells) in neurofibroma tissue sections PPTN treated mice." (PMID 35311647, 2022). "P2RY14 deletion in a mouse model of neurofibroma increases survival and delays neurofibroma initiation." (PMID 35311647, 2022). "Gross dissection of spinal cords from these mice showed that P2ry14-/-;Nf1fl/fl;DhhCre have decreased neurofibroma number, consistent with a role in tumor initiation, and only slightly reduced neurofibroma diameter." (PMID 35311647, 2022). "We conclude that genetic knockout of P2ry14 in neurofibroma-bearing mice improves the Remak bundle defects characteristic of neurofibroma-bearing mice, and that are present in both nerve and neurofibroma." (PMID 35311647, 2022). "Kaplan-Meier survival analysis showed that P2ry14-/-; Nf1fl/fl;DhhCre have a significant survival advantage compared to neurofibroma-bearing mice (Nf1fl/fl;DhhCre; p = 0.0256)." (PMID 35311647, 2022). "Anti-P2ry14 staining also showed P2ry14 protein membranes of myelinating SCs in human neurofibroma tissue sections." (PMID 35311647, 2022). "Based on these results, we conclude that P2ry14 deletion in vivo in neurofibroma mice increases mouse survival and delays neurofibroma initiation and has lesser effects on SC proliferation." (PMID 35311647, 2022). "In vivo, neurofibroma bearing mice treated with either rolipram or the P2ry14 inhibitor showed increases in pPKA expression and decreases in SC proliferation after treatment." (PMID 35311647, 2022). "In a mouse model of NF1, genetic deletion of P2ry14 rescued low cAMP signaling, increased mouse survival, delayed neurofibroma initiation, and improved SC Remak bundles." (PMID 35311647, 2022). "Genotyping and western blotting verified reduced P2ry14 in P2ry14-/-; Nf1fl/fl;DhhCre sciatic nerve and neurofibroma tumors compared to Nf1fl/fl;DhhCre controls." (PMID 35311647, 2022). "We identified the G-protein-coupled receptor (GPCR) P2ry14 in human neurofibromas, neurofibroma-derived SC precursors (SCPs), mature SCs, and mouse SCPs." (PMID 35311647, 2022). "To test if P2RY14 deletion plays a role in neurofibroma initiation, we analyzed Nf1fl/fl;DhhCre and P2ry14 -/-;Nf1fl/fl;DhhCre mice to 4 months of age, when tumor is first detectable." (PMID 35311647, 2022). "(D) Neurofibroma diameter quantification at 7 months (unpaired t-test ***p = 0.0004) (for C and D: Nf1fl/fl;Dhh+ n = 8 mice, 48 neurofibroma tumors; P2ry14-/-;Nf1fl/fl;Dhh+ n = 8 mice, 11 neurofibroma tumors)." (PMID 35311647, 2022). "Thus, P2ry14 is overexpressed in human neurofibroma SCPs in vitro, and marks SCP with the potential to self-renew in vitro." (PMID 35311647, 2022). "We identified P2ry14 as a G-protein-coupled receptor (GPCR) expressed in neurofibroma SCPs." (PMID 35311647, 2022). "In either case, neurofibroma also contain cells that also express P2ry14." (PMID 35311647, 2022). "Similarly, there may be a connection between the self-renewal of Schwann cell precursors and neurofibroma development through the purinergic receptor P2Y14 (P2RY14)/cAMP signaling pathway." (PMID 35805104, 2022). "Altogether, these in vitro and in vivo studies show that in a mouse model of neurofibromatosis, P2ry14 is a key regulator of SCP self-renewal, SC proliferation, neurofibroma initiation, and neurofibroma maintenance." (PMID 35311647, 2022).
neurofibroma (continued). "FACS analysis (of cells from three additional neurofibroma tumors) showed that on average p75+/EGFR+/P2ry14- cells formed spheres at a frequency of 23.4%, while 64.8% of p75+/EGFR+/P2ry14+ cells formed spheres." (PMID 35311647, 2022). "We found that elevation of cAMP by either blocking the degradation of cAMP or by using a P2ry14 inhibitor diminished NF1-/- SCP self-renewal in vitro and neurofibroma SC proliferation in in vivo." (PMID 35311647, 2022). "While the P2ry14 inhibitor (PPTN) has poor PK properties, when drug candidates targeting P2ry14 become available, they may be useful for prevention or treatment of NF1-driven neurofibromas." (PMID 35311647, 2022).
acute lymphoblastic leukemia (1 paper, 2018). Leukemia with an acute onset, characterized by the presence of lymphoblasts in the bone marrow and the peripheral blood. "We observed that acute lymphoblastic leukemia (ALL) and FLT3-ITD-positive acute myeloid leukemia (AML) patients with higher expression of P2RY14 mRNA displayed relatively poor survival compared to patients carrying lower expression of P2RY14 suggesting a role of P2RY14 in patient survival." (PMID 29951132, 2018).
brain tumors (1 paper, 2025). "Gene profiling revealed that BV2 cells expressed higher levels of both M2‐associated genes (Maf, Selenop, P2ry14, Mrc1, Ctsc, and Cxcr4) and M1‐associated genes (Il7r, Atf3, and Gadd45g) compared to RAW264.7 cells, suggesting its multifaceted role in interaction with brain tumors." (PMID 40747560, 2025).
colorectal cancer (1 paper, 2022). A primary or metastatic malignant neoplasm that affects the colon or rectum. "Two of the last-mentioned hub genes (P2RY14, and NPY1R), to the best of our knowledge, have not already been reported as being under-expressed in colorectal cancer." (PMID 35333898, 2022).
esophageal squamous cell carcinoma (1 paper, 2023). Esophageal squamous cell carcinoma (ESCC) is a type of esophageal carcinoma (EC) that can affect any part of the esophagus, but is usually located in the upper or middle third. "Previous studies showed that COL1A1, RAB27A, and P2RY14 were identified as the potential biomarker for esophageal squamous cell cancer (ESCC) and RAB27A associated with immune infiltration in ESCC7,18–20." (PMID 36759514, 2023).
neurofibromatosis (1 paper, 2022). A hereditary neoplastic syndrome in which tumors grow in the nervous system. "In conclusion, P2ry14 cAMP signaling regulates SCP self-renewal and nerve tumor initiation in neurofibromatosis." (PMID 35311647, 2022).
Obesity (1 paper, 2016). Accumulation of substantial excess body fat. "Inflammation and immunity: Culture with Dex led to a more robust increase in Abdsc than Om of CD300LG which is implicated in T-cell recruitment and P2RY14/GPR105 (Cluster 1) which modulates macrophage recruitment in diet-induced obesity." (PMID 28005982, 2016).
oral cancer (1 paper, 2024). "We further examined the expression of CCR4, CXCR3, P2RY14, CCR2, CCR8, and CCL19 in highly aggressive oral cancer cell lines and tissues." (PMID 38213736, 2024). "The expression of CCR4, CXCR3, CCR2, and CCR8 was higher in highly invasive oral cancer cell lines (SCC-25, CAL-27, and FaDu) than in the less aggressive cell line (HSC-2), whereas CCL19 and P2RY14 expression showed the opposite trend." (PMID 38213736, 2024). "Further analysis of gene expression in clinical tissues revealed that CCR4, CXCR3, CCR2, and CCR8 exhibited higher expression in oral cancer cells of patients with metastasis compared to those without, whereas CCL19 and P2RY14 displayed the opposite trend." (PMID 38213736, 2024).
status epilepticus (1 paper, 2018). Status epilepticus is defined as a continuous seizure lasting more than 30 min, or two or more seizures without full recovery of consciousness between any of them. "Status epilepticus: Increased P2ry2, P2ry4, and P2ry6 and decreased P2ry1, P2ry12, P2ry13, and P2ry14 transcript levels; increased P2Y1, P2Y2, P2Y4, and P2Y6 and decreased P2Y12 protein levels." (PMID 29563872, 2018).